NGF (nerve growth factor)
Diseases named in the same sentence as NGF in open-access papers (continued):
Sharing a sentence is not in itself a finding about the gene and the disease.
osteonecrosis (9 papers, 2016 to 2025). A none disease characterized by death of bone tissue due to a lack of blood supply. "By reviewing the adverse events reported in clinical trials, it was found a dose-response relationship between osteonecrosis and NGF antibodies, with the dose of Tanezumab ranging from 2.5 to 10 mg and the dose of Fasinumab ranging from 3 to 9 mg." (PMID 33935742, 2021). "In clinical trials of the monoclonal NGF antibody tanezumab for knee and hip OA pain, osteonecrosis was reported as a side effect." (PMID 29100502, 2017). "However, the most problematic issue is that, the US Food and Drug Administration (FDA) suspended anti-NGF clinical trials in 2010 because of a high incidence of osteonecrosis." (PMID 27294371, 2016). "Clinical observations with recently developed neutralizing antibodies to NGF have shown a high incidence of osteonecrosis and rapidly progressive osteoarthrosis, which may be another reflection of impaired angiogenesis in the context of neurotrophin antagonism." (PMID 34400627, 2021). "It should be noted that anti-NGF treatment may lead to treatment-related rapidly progressive OA (PROA) and osteonecrosis." (PMID 33935742, 2021).
systemic lupus erythematosus (9 papers, 2013 to 2025). An autoimmune multi-organ disease typically associated with vasculopathy and autoantibody production. "More recently, it was also demonstrated that circulating levels of NGF and BDNF are increased in SLE patients, with severe lupus flares showing augmented NT-3 levels." (PMID 31616373, 2019). "Therefore, we examined the correlation between enhanced NGF and BDNF levels and lupus systemic activity." (PMID 24223945, 2013). "Systemic Lupus Erythematosus (SLE) patients exhibit a significant increase in NGF concentration in the sera, which correlates with disease activity, and similar findings were obtained in studies of NZB/W mice, a spontaneous model of human SLE." (PMID 28492466, 2017).
viral infection (9 papers, 2009 to 2024). "In other systems, the high circulating and tissue NGF levels upon viral infection were associated with a neuroprotective function, such as in viral conjunctivitis or in keratoplasty when Herpes Simplex reinfections might be induced upon surgical stress." (PMID 36579579, 2022). "In addition, the multivariate analysis revealed NGF and NGFR levels, BMI scores, virus infection, and tumor stage as the independent risk factors for OS, DSS, DFI, and PFI." (PMID 38204220, 2024). "NGF has been shown to be involved in cell protection within the nervous and immune systems during viral infections, and may confer resistance against other virus." (PMID 19649262, 2009). "For example, antibodies against NGF have been discovered in the sera of herpes simplex virus (HSV) patients, suggesting a possible role in modulating NGF’s cytokine function during viral infection." (PMID 37998739, 2023). "the participation of NGF and BDNF in viral infections, chronic lung inflammation, and tissue remodeling (fibrosis)-associated states; ii." (PMID 36579579, 2022). "Nerve growth factor (NGF) is overexpressed in patients with inflammatory lung diseases, including virus infections." (PMID 25347857, 2014). "Two of the most studied are nerve growth factor (NGF) and brain-derived neurotrophic factor (BDNF), which are released by inflammatory cells and by airway epithelium in the setting of allergen exposure, virus infection, and other insults." (PMID 34557110, 2021). "Therefore, the increased levels of NGF and BDNF might be viewed as an outcome of the immune response to viral infection." (PMID 36579579, 2022). "Some factors, including nerve growth factor (NGF) and pigment epithelium-derived factor (PEDF), have been shown to be effective at accelerating corneal sensitivity after LASIK and in promoting corneal nerve regeneration in preclinical models of nerve injury post-viral infection respectively." (PMID 32366307, 2020).
allergic asthma (8 papers, 2012 to 2024). A asthma with a basis in a pathological type I hypersensitivity reaction. "Some studies have indicated that anti-NGF decreased airway hyperresponsiveness caused by allergen challenge, and this could be a therapeutic strategy for the treatment of allergic asthma." (PMID 23137120, 2012). "Allergic asthma and rhinitis are characterized by high NGF and BDNF levels in both serum and bronchoalveolar lavage fluid, especially after allergic stimulation." (PMID 38534776, 2024). "Another study also found significantly higher serum levels of NGF in patients with AR, allergic asthma, and urticaria-angioedema in comparison to control subjects." (PMID 37047077, 2023). "For allergic asthma, higher NGF levels in BALF have also been reported and were found to be elevated even further after segmental allergen provocation." (PMID 37047077, 2023). "In conclusion, a wide variety of studies have demonstrated that aside from BDNF, NGF is the best-characterized neurotrophin in AD, AR, allergic asthma, and even ARC." (PMID 37047077, 2023). "The findings concerning NGF in AR, allergic asthma, and also ARC validate that these neurotrophins are worth putting into the spotlight of investigation." (PMID 37047077, 2023). "In response to allergen stimulation, serum, and BALF from patients with allergic asthma exhibit highly increased levels of NGF correlating with the degree of airway hyperreactivity." (PMID 28861085, 2017). "A switch to a Th2 cell response seems to increase NGF secretion, and this observation may be relevant concerning allergic asthma." (PMID 38534776, 2024). "Additionally, we demonstrate that vitamin D plays a protective role, in vitro, in PM-exposed allergic asthma by regulating the Nrf2/HO-1 and NGF signaling pathways." (PMID 38273268, 2024). "Together, the findings of increased local NGF and receptor expression levels, the involvement of SP, and the tendency of NGF to induce Th2 inflammation indicate an important role for the neurotrophin not only in skin diseases such as AD but also in AR and allergic asthma." (PMID 37047077, 2023). "The direct role of NGF in allergic asthma has been demonstrated in a mouse model of the disease." (PMID 37047077, 2023). "Further, the preincubation of WT pDCs with NGF strongly enhances the symptoms of allergic asthma." (PMID 28861085, 2017). "Therefore, further in vivo study is required to verify whether NGF may promote lung DC maturation in the background of allergic asthma." (PMID 25289030, 2014). "Therefore, downregulating NGF levels may benefit patients with allergic asthma." (PMID 25289030, 2014).
cardiac hypertrophy (8 papers, 2009 to 2024). "Our pathway analysis of the downstream targets of miRNAs 155-5p and 302a-3p implicated them in the regulation of adipogenesis, cardiac hypertrophy, IL-8, and NGF signaling." (PMID 31475159, 2019). "The predicted targets of the miRNAs identified were implicated in the regulation of cardiac hypertrophy, adipogenesis, interleukin-8 (IL-8), and nerve growth factor (NGF) signaling." (PMID 31475159, 2019). "It is well known that ET-1 expression is increased in cardiac hypertrophy and that NGF is specifically induced by this ET-1 in cardiomyocytes, indicating that the ET-1/NGF pathway is important for cardiac sympathetic innervation during heart development." (PMID 36160916, 2022). "NTs affect cardiovascular development via the nervous system, as cardiac muscle-specific NGF overexpression induces cardiac hypertrophy via hyperinnervation." (PMID 34827728, 2021). "As discussed, regarding the mechanism, NGF derived from cardiomyocytes can control sympathetic nerve density when the heart is damaged by heart failure or cardiac hypertrophy." (PMID 34827728, 2021). "Up-regulation of NGF production by cardiomyocytes was observed in cardiac hypertrophy and upon endothelin-1 treatment." (PMID 24244423, 2013). "In a previous study we report that NGF is upregulated in cardiac hypertrophy, leading to sympathetic hyperinnervation and rejuvenation." (PMID 21037846, 2009). "The most significantly affected signaling pathways were EIF-2, IL-2, integrin, NGF, VEGF, estrogen receptor, IL-7, FLT3, FGF, oxytocin, cardiac hypertrophy, role of NFAT in cardiac hypertrophy, and neutrophil extracellular trap pathways." (PMID 38047311, 2024). "These include cardiac hypertrophy signaling, CREB signaling in neurons, P2Y purinergic receptor signaling, and NGF signaling." (PMID 29088840, 2017).
colitis (8 papers, 2014 to 2026). Inflammation of the colon. "Supporting these findings, immunoneutralization of NGF caused an exacerbation of experimentally induced colitis, suggesting that this factor, together with others, plays a regulatory role in intestinal inflammation." (PMID 41301953, 2025). "Colitis significantly activated CHRNA3+ nociceptors via the NGF-TrkA/pERK/PIEZO2 pathway, converting them from mechanoinsensitive to mechanosensitive." (PMID 42157236, 2026). "A CGRP antagonist, CGRP 8–37, attenuates colitis or nerve growth factor (NGF)-induced visceral hypersensitivity in male rats." (PMID 38786056, 2024). "During colitis, similar modulation in the expression of sensory-related markers was observed in both genotypes, where the NGF mRNA levels were downregulated by colitis in both genotypes (p < 0.05 vs. healthy WT and σ1R KO mice, respectively)." (PMID 37893131, 2023). "Neutralization with anti-NGF antibodies of the enhanced production of NGF increased the disease symptoms with a higher number of infiltrating neutrophils and macrophages and more extended gut lesions in animal models of colitis." (PMID 28492466, 2017). "However, in a study conducted in a mouse model in which colitis was experimentally induced, a reduction in the expression of various neurotrophins, including NGF, was detected in rat colonic smooth muscle cells." (PMID 41301953, 2025). "Overall, the gene expression changes detected in the vehicle-treated mice exposed to DSS were similar to those reported in the first experiment, with a tendency for a general downregulation during colitis, although in this case, statistical significance was only reached for NGF and TRPV1." (PMID 37893131, 2023). "Indeed, ectopic expression of NGF in the intestinal epithelium has been shown to improve intestinal recovery, following dextran sulfate sodium-induced colitis in mice." (PMID 30988299, 2019). "This plasticity of TRPV1 expression may be a more general feature of chronic pain signals since a recent study found that during colitis TRPV1 protein levels were significantly increased by nerve growth factor (NGF) in specific rat colonic afferent neurons of both L1 and S1 DRG neurons." (PMID 38919332, 2024). "However, opposite results have been observed in other studies in which blocking NGF through the administration of anti-NGF antibodies was effective in reducing colonic hyperalgesia in murine models of colitis, suggesting that NGF may represent a therapeutic target for pain related to this disease." (PMID 41301953, 2025). "Recent animal studies with systemic drug intervention by injecting antiserum of either NGF or BDNF to rats with colitis suggested a possible interaction of the NGF and BDNF pathways in colitis-induced visceral hypersensitivity." (PMID 24788240, 2014).
dermatitis (8 papers, 2009 to 2024). An inflammatory process affecting the skin. "Since HGF and NGF are recognized melanogenic paracrine factors associated with solar lentigo and melasma pathogenesis, common hyperpigmentary skin disorders 52-55, the anti-melanogenic activity of altiratinib could potentially be mediated by interfering with these signaling pathways." (PMID 34815795, 2021). "In addition, CB2 agonists suppress skin inflammation by inhibiting inflammatory cell migration, and GPR55, which is found in mast cells, has anti-inflammatory effects by inhibiting mast cell-mediated release of nerve growth factor and reducing angiogenesis." (PMID 32063982, 2020).
heart failure (8 papers, 2011 to 2025). Inability of the heart to pump blood at an adequate rate to meet tissue metabolic requirements. "In severe heart failure, continuous norepinephrine infusion induces a loss of sympathetic fibers, presumably because of NGF reduction." (PMID 34827728, 2021). "In a mouse model of heart failure associated with diabetic cardiomyopathy, NGF gene therapy with adeno-associated vectors has been shown to be a potential drug candidate." (PMID 34827728, 2021). "One study showed that MI-induced heart failure can promote breast cancer growth via the NGF-TRKA pathway." (PMID 39634266, 2024). "Reduced NGF levels were also seen in a zebrafish model of heart failure and, upon NGF administration, cardiomyocyte proliferation increased and cardiac regeneration restored." (PMID 32825069, 2020). "The present study demonstrates, for the first time, the ability of NGF to repair the heart by inducing cardiomyocyte proliferation in an experimental model of heart failure in larval zebrafish." (PMID 23300892, 2012). "To determine the mechanism by which NGF prevented the development of heart failure, we considered the dual possibilities that NGF exerted an anti-apoptotic effect or facilitated cardiac regeneration." (PMID 23300892, 2012). "Specifically, we have previously shown that marked alterations occur in the activity of the cardiac sympathetic nervous system in heart failure, together with a substantial depletion of nerve growth factor in the heart." (PMID 23300892, 2012). "To support our contention that reduced tissue NGF levels contribute to the pathogenesis of the response to cardiac injury and heart failure we evaluated the levels of NGF mRNA expression in AA treated zebrafish hearts." (PMID 23300892, 2012). "In a zebrafish model of cardiac injury, NGF reduced the incidence of heart failure and mortality." (PMID 34827728, 2021). "We hypothesise that NGF may provide a more favourable environment which sufficiently regenerates the heart to prevent the development of heart failure." (PMID 23300892, 2012). "Guizhi Decoction, Guizhi Decoction, comprising ingredients like Guizhi and ginger, improves myocardial fibrosis by modulating NGF and LIF levels, slowing heart failure progression." (PMID 40606601, 2025). "Nerve growth factor (NGF) has an important role in modulating sympathetic nerve structure and function, density of sympathetic innervation, and the formation and persistence of heart failure." (PMID 35928246, 2022). "UBN1, NGF and FECH genes displayed similar statistically significant regulation (up or down regulated) in hearts samples from heart failure patients but expression of the three remaining genes (TMEM79, FBXW7 and SLC43A2) could not be quantified, probably because of their low expression in heart." (PMID 21731613, 2011).
hereditary sensory and autonomic neuropathy type 5 (8 papers, 2011 to 2025). Hereditary sensory and autonomic neuropathy, type 5 (HSAN5) is characterized by loss of pain perception and impaired temperature sensitivity, in the absence of any other major neurological anomalies. "It has also been found that mutations in the NGF gene cause the so called “painlessness disease”, hereditary sensory and autonomic neuropathy type V (HSAN5)." (PMID 40362318, 2025). "Accordingly, mutations in the NGF gene cause a disease characterized by pain insensitivity called Hereditary Sensory and Autonomic Neuropathy type V (HSAN V)." (PMID 35681529, 2022). "A point mutation in the Nerve Growth factor gene (leading to the amino acid substitution R100W), causing Hereditary Sensory and Autonomic Neuropathy type V, a condition that primarily affects the sensory nerve cells, whose principal function is to transmit information about sensations, such as pain." (PMID 36979056, 2023). "Bi-allelic dysfunctional mutations in nerve growth factor (NGF) cause the rare human phenotype hereditary sensory and autonomic neuropathy type 5 (HSAN5)." (PMID 30296891, 2018). "Mutations in NGF cause the rare autosomal recessive disorder hereditary sensory and autonomic neuropathy type 5 (HSAN5, online mendelian inheritance in man #608654)." (PMID 30296891, 2018). "To this aim, we described a “painless” form of NGF, linked to the rare human genetic disease HSAN V (Hereditary Sensory Autonomic Neuropathy Type V)." (PMID 22666365, 2012). "In this study we exploit forms of NGF, mutated at residue R100, inspired by the human genetic disease HSAN V (Hereditary Sensory Autonomic Neuropathy Type V), which would allow increasing the dose of NGF without triggering pain." (PMID 22666365, 2012).
infarction (8 papers, 2013 to 2023). A localised pathological necrosis of tissue resulting from obstruction of the blood supply usually by a thrombus, an embolus, or vascular torsion. "It is also of interest that increased levels of NGF have a crucial role in post-infarction cardiac remodeling." (PMID 37373824, 2023). "Nevertheless, some studies found that NGF pretreatment relieved myocardial infarct damage in the diabetic heart or physiologically normal heart by using a Langendorff system or in in vivo rat model of myocardial regional ischemia-reperfusion injury." (PMID 34471416, 2021). "Increased myocardial superoxide and nitrotyrosine levels were noted post-infarction, in addition to a significant upregulation of NGF expression on mRNA and protein levels." (PMID 30153299, 2018). "The clinical manifestations of the canine infarction model treated by NGF were significantly improved within 7 days compared with control group." (PMID 29423079, 2018). "In the present study, we demonstrated for the first time that infarction was associated with an increased resistin expression via the GIP-dependent pathway, subsequently leading to an increased NGF expression both in vivo and ex vivo." (PMID 26811539, 2016). "Among these factors, nerve growth factor (NGF) is recognized to play an important role in post-infarction remodeling." (PMID 24755692, 2014). "Western-blot experiments showed a significant overexpression of both immature proNGF and mature NGF in the infarction scar of rat hearts when compared to control tissue." (PMID 24244423, 2013). "However, this is the first study to evaluate the association of the genetic variations of the NGF and the NGFR genes with IS, infarction size and recurrence of the disease in Armenian population." (PMID 29499660, 2018).
knee osteoarthritis (8 papers, 2015 to 2026). "Together, this provides evidence that PPS may act at multiple levels to suppress the release of NGF and potentially other pain mediators in the subchondral bone, to ameliorate pain associated with knee osteoarthritis." (PMID 31557169, 2019). "Together, this provides evidence that PPS may act to suppress the release of NGF in the subchondral bone to ameliorate pain associated with knee osteoarthritis." (PMID 31557169, 2019). "In fact, tanezumab, a humanized monoclonal antibody targeting NGF, showed potential in managing pain and improving function in patients with knee osteoarthritis." (PMID 39457530, 2024). "Here, we aimed to clarify the efficacy of NGF antibody in a knee osteoarthritis (OA) pain model in mice." (PMID 29100502, 2017). "Knee osteoarthritis (KOA) pain is caused by nociceptors, which are actually sensory nerve fiber endings that can detect stimuli to produce and transmit pain signals, and high levels of NGF in synovial tissue led to peripheral hyperalgesia in KOA." (PMID 38410126, 2024). "Joint pain in knee osteoarthritis may be both nociceptive and neuropathic and is the result of complex mechanisms driven by nerve growth factor, calcitonin gene-related peptide and pro-inflammatory cytokines." (PMID 38275369, 2023). "Nerve growth factor (NGF) contributes to pain in knee osteoarthritis (KOA) patients." (PMID 31077183, 2019).